SNORD16 (small nucleolar RNA, C/D box 16)
Synonyms: U16
Gene: Small nucleolar RNA gene on chromosome 15 (66,502,812 to 66,502,910, reverse strand). Ensembl gene ENSG00000199673.
Gene Ontology:
Biological process: RNA processing
Cellular component: nucleolus
Homologues: Orthologues: chimpanzee SNORD16 (100% identical), macaque SNORD16 (99% identical), dog SNORD16 (98% identical), guinea pig SNORD16 (95% identical), pig SNORD16 (95% identical), mouse Snord16a (94% identical), pig SNORD16 (94% identical), rabbit SNORD16 (93% identical), rat SNORD16 (93% identical), pig SNORD16 (92% identical), tropical clawed frog SNORD16 (79% identical), zebrafish SNORD16 (79% identical).
Diseases named in the same sentence as SNORD16 in open-access papers:
SNORD16 is named in the same sentence as 4 diseases in open-access papers, as found by Europe PMC text mining. Sharing a sentence is not in itself a finding about the gene and the disease. The quoted sentences say what the papers report.
colon cancer (2 papers, 2021 to 2022). "In colon cancer, SNORD16 promotes tumorigenesis, and SNORD16 knockdown restrains the proliferated, migrated, and invaded ability of colon cancer cells and promotes apoptosis." (PMID 34047477, 2021).
breast carcinoma (1 paper, 2025). "SNORD16, SNORA73B, SCARNA4, and SNORD49B were found to be upregulated in both breast cancer and early-stage breast cancer, and have emerged as potential biomarkers for the diagnosis of these conditions." (PMID 40264043, 2025).
glaucoma (1 paper, 2023). Increased pressure in the eyeball due to obstruction of the outflow of aqueous humor. "Additionally, SNORD3A, SNORD16, SNORA52, and SNORA23 were differentially expressed in patients with glaucoma." (PMID 37805546, 2023).
cancer (1 paper, 2024). A tumor composed of atypical neoplastic, often pleomorphic cells that invade other tissues. "Therefore, we believe that SNORD16, SNORD73B, SCARNA4, and SNORD49B are significant contributors to the development and spread of cancer, even if additional study is required to elucidate their potential molecular pathways." (PMID 38311725, 2024).